CDKN1B (cyclin dependent kinase inhibitor 1B)
Diseases named in the same sentence as CDKN1B in open-access papers (continued):
Sharing a sentence is not in itself a finding about the gene and the disease.
tumor (continued). "The time interval between birth and the first aggressive tumour was significantly shorter in patients with the CDKN1B V109G polymorphism (median 46 years) than in those without (median not reached; P = 0.03)." (PMID 25824098, 2015). "Transcription of specific genes like MCM3 and CDKN1B effects tumor suppressor ability of BAP1." (PMID 26680512, 2015). "HPV-16 E7 protein can modulate the cytoplasmic localization of CDKN1B (p27KIP1) and may, in turn, regulate tumor metastasis/aggressiveness through the PI3K/AKT pathway." (PMID 26239469, 2015). "The CDKN1B gene is therefore considered to be an atypical tumor suppressor gene." (PMID 25416039, 2015). "ETV6 and CDKN1B are the candidate tumor suppressor genes within the region 12p13." (PMID 25213837, 2014). "Unlike other tumor suppressors and negative regulators of the cell cycle, the p27 gene CDKN1B, is rarely mutated in human cancers but instead p27 levels are highly regulated by post-translational modifications." (PMID 23029392, 2012). "Based on these findings, we hypothesized that RB is essential for the progression of Inha KO tumorigenesis and, similar to Inha/Cdkn1b dKO, that Inha/Rb dKO mice would demonstrate rapid tumor formation." (PMID 20676395, 2010). "The downregulation of CDKN1B found in prostate lesions in Men1 mutant mice suggests the in vivo importance of CDKN1B inactivation in the tumorigenesis related to Men1 inactivation, similar to observations in other mouse Men1 tumour models." (PMID 20663219, 2010). "Consistent with a tumor suppressor function, mice lacking one or both copies of the Cdkn1b gene have increased susceptibility to carcinogen-induced tumorigenesis." (PMID 18941537, 2008). "Among many genes in this pathway, SKP2 was found over-expressed in basal-like tumors; it encodes a protein involved in the degradation of another cyclin-dependent kinase inhibitor p27 (CDKN1B) and recently reported to be over-expressed in many tumor types and to correlate with poor prognosis." (PMID 16729877, 2006). "Furthermore, another key tumor suppressor downregulated by skp2 is the negative cell cycle regulator p27 encoded by CDKN1B which was also shown in our study to be upregulated by the combination." (PMID 38489280, 2024). "CDKN1B is not considered a typical tumor suppressor because it is very lightly mutated in tumors." (PMID 35832790, 2022). "Whereas in other tumor types it is not uncommon to find genes that are mutated in 50–95% of cases, in I-NETs the gene that is most frequently associated with point mutations is CDKN1B, which is mutant in only 8% of cases." (PMID 34680217, 2021). "Therefore, Dll4/Notch inhibition may also negatively affect the tumor stem cell populations through Atoh1 derepression-mediated upregulation of the CDK inhibitors Cdkn1b and Cdkn1c." (PMID 28086833, 2017). "Both FOXO3A and MYC interact functionally with the forkhead binding element in the CDKN1B proximal promoter, meaning that MYC may inhibit the activation of CDKN1B by FOXO3A in tumor cells, potentially leading to the uncontrolled proliferation and invasiveness of a variety of tumors." (PMID 29124072, 2017). "Interestingly CDKN1B was down-regulated both in tumour versus normal and after resistance." (PMID 22905093, 2012). "p27Kip1 does not follow Knudson's classic “two-hit hypothesis” of tumor suppression because homozygous loss or silencing of the Cdkn1b locus in human tumors is extremely rare." (PMID 18941537, 2008). "Elevated CDC20 levels facilitate the ubiquitination and degradation of CDKN1B, a G1/S phase cell cycle inhibitor, driving GBM cell proliferation and tumor progression." (PMID 40565099, 2025).
tumor (continued). "The overexpression of miR-155 not only downregulates critical tumour suppressor genes, such as FOXO3 and CDKN1B, but also plays a well-documented pro-fibrotic role in various fibrotic conditions by promoting the synthesis of ECM proteins, including collagen." (PMID 41007812, 2025). "In HCC, co-administration of miR-122 mimics (a tumor suppressor) and miR-221 inhibitors synergistically reduces tumor growth by restoring PTEN and CDKN1B/p27 expression." (PMID 41369385, 2025). "We also observed enrichment of sgRNAs targeting CDKN1B, PTEN, TSC1 and TSC2 in both cell types, suggesting deletion of these tumor suppressors provides a survival advantage." (PMID 38480701, 2024). "Proliferation and tumor studies exhibited a decrease in growth and an upregulation of dormancy markers, such as NR2F1 and CDKN1B." (PMID 39199676, 2024). "The CDK inhibitors of the CDK interacting protein (KIP) family, more especially CDKN1B/p27 and CDKN1C/p57, are two more proteins that play a role in HCC tumor suppression and direct cell cycle regulation." (PMID 38799446, 2024). "The best‐described role for FOXO factors in cancer is to serve as tumor suppressors that induce genes such as TRAIL (TNFSF10) to promote apoptosis and p27 (CDKN1B) to halt the cell cycle." (PMID 36602390, 2023). "For instance, the cyclin-dependent kinase inhibitors (CDKs), CDKN1A (p21Cip1), CDKN1B (p27Kip1), and CDKN2A (p16Ink4A), reprimo (RPRM), stratifin (SFN), and CDK1 are all frequently hypermethylated and play various roles in tumor radioresistance." (PMID 37455903, 2023). "The minimally-deleted region of 12p spans 2.75Mb, and includes the gene bodies of 18 protein-coding genes, including the tumor suppressors ETV6 and CDKN1B." (PMID 36711871, 2023). "We also observed enrichment of sgRNAs against CDKN1B, PTEN, TSC1 and TSC2 in both cell types, suggesting deletion of these tumor suppressors provides a survival advantage." (PMID 37502925, 2023). "The G1 checkpoint cyclin-dependent kinase inhibitor 1B (CDKN1B, p27kip1, or p27) plays a crucial role in tumor suppression by binding to and preventing the activation of cyclin E-CDK2 complexes, thus inhibiting abnormal cell cycle progression." (PMID 35892829, 2022). "Compared with normal samples, the expression level of CASP7, CDKN1B, EIG4G1, and EIF4EBP1 were significantly increased in the primary tumor samples, while that of CDH3 was significantly decreased." (PMID 35787690, 2022). "We observed significant upregulation of miR-200b (p = 0.003) and ONECUT2 (p = 0.018) in the tumour tissue of CRC pT3 compared to the corresponding normal mucosa, as well as downregulation of CDKN1B (p = 0.013)." (PMID 36140249, 2022). "In lymph node metastases compared to the invasive front of the tumor, ONECUT2 and SOX2 were down-regulated, while PTPN13, TGFB2, ZEB2, RND3 and CDKN1B were up-regulated." (PMID 34046357, 2021). "Two tumor suppressor genes and corresponding proteins i.e. SMAD4, and CDKN1B, were further characterized using a tissue microarray (TMA) with 846 SINETs." (PMID 33509126, 2021). "MLL binds to the promoter regions of cyclin-dependent kinase inhibitors (CDKis) p18Ink4c (CDKN2C) and p27Kip1 (CDKN1B), maintaining the expression of these genes and inhibiting tumour formation." (PMID 34439335, 2021). "The PCR array result showed, ectopic expression of TTPAL activated the expression of PI3K/AKT signaling-related genes while downregulated tumor suppressors, such as RBL2, PTEN, and CDKN1B (p27)." (PMID 34642500, 2021). "Conversely, CDKN1B, a cyclin-dependent kinase inhibitor, is frequently down-regulated in CRC, with an aggressive tumor behavior and a poor clinical outcome." (PMID 32164324, 2020).
tumor (continued). "Accordingly, in MCF-7 TIE2tet cells, induction of the expression of TIE2 with Dox-induced a significant increase of the cyclin-dependent kinase (CDK) inhibitors CDKN1A (or P21CIP1) and CDKN1B (or P27KIP1), as previously reported in dormant tumor cells." (PMID 32260072, 2020). "Five of these signaling proteins (CDKN1B, CDKN1C, PTN, GJA1, and MORF4L2) can act as tumor suppressors." (PMID 32168333, 2020). "These pathways were all connected to tumor growth, and the PI3K/Akt signaling pathway (eight involved genes: CCND2, CDKN1B, CSF1, EFNA3, FGFR2, FGFR3, IL2RB, and ITGA9) ranked first among upregulated pathways (Enrichment Score = 3.159187)." (PMID 30755239, 2019). "miR-200b was found to be down-regulated in tumour budding cells at the invasive front in 71% of cases and is believed to have a tumour-promoting role in CRC by targeting RND3 and CDKN1B." (PMID 31623346, 2019). "The genes most frequently showing CNGs in HAS tumour tissues were TOP1 (50.0%), STK4 (45.5%), CDKN1B (40.9%), H3F3A (36.4%), MYC (22.7%), CCNE1 (22.7%), NFKBIA (22.7%), VEGFA (18.2%), CCND3 (13.6%), and E2F1 (13.6%)." (PMID 30989433, 2019). "Several important cell cycle regulators were found differentially expressed in the reprogrammed tumours, including CDK4, E2F5, and CDKN1B (P27), WEE1, CDKN3." (PMID 29662623, 2018). "No known oncogenes were found mutated, but four of the seven patients (GIST_150, _174, _124 and _188) showed deleterious mutations in two candidates (KEAP1 and LATS2) and in three well-known tumor suppressors (CDKN2A, CDKN1B and PTEN)." (PMID 26544626, 2015). "For example, CDKN1B directly binds and inhibits CDK6 (known to have a tumor suppressive role), whose underexpression implies a poor prognosis." (PMID 25425654, 2014). "Molecular silencing of HDAC1 using small interfering RNA (siRNA) attenuated VPA-mediated regulation of CDKN1A, CDKN1B and LC3-I/II, regression of tumor cell growth and induction of autophagy." (PMID 23866964, 2013). "We selected 5 known tumor-related genes i.e., K-ras, c-MYC, DNMT1, Tpd52, CDKN1b for PCR confirmation." (PMID 22206623, 2011). "Tumour tissue and normal tissue group of five candidate reference genes (CASC3, CDKN1B, POLR2A, PUM1 and UBC) were statistically equivalent to within ± 1.5." (PMID 21806841, 2011). "To validate our experimental conditions we next measured in Akata cells the expression of cellular genes known to be reactivated by Zebularine in other tumor cell lines including CDKN1A, CDKN1B and CDKN2A genes." (PMID 17214905, 2007). "While these molecular signatures distinguish tumour aggressiveness, only age and certain cell cycle genes (CDK4, CDKN1B) achieved independent prognostic significance in multivariate models, underscoring the need for further validation of molecular risk markers." (PMID 41007296, 2025). "We identified 42 and 16 TSGs monoallelically deleted in P2 and P5, respectively, including several TSGs deleted in both tumor samples (ARHGEF10, CDKN1B, ETNK1, ETV6, LEPROTL1, NRG1, PTPN6, and WRN) and many TSGs co-deleted in the same subclone as well as across multiple subclones." (PMID 38658552, 2024). "In only one pair of tumors, extensive genomic differences in the recurrent tumor that were not present in the primary tumor, were found such as CDKN1B (rs146973564, c.C365T, p.P122L) and MLH1 (rs1799977, c.A655G, p.I219V) among others." (PMID 39217365, 2024). "Interestingly, genes with oncogenic potential, including CDC42, CDC14B, STK40, BRD3, CPNE1, and MCM3, were downregulated, whereas tumor inhibitors, including CDKN2C, CASP7, and CDKN1B, were upregulated by RBM15 depletion." (PMID 38825643, 2024).
tumor (continued). "In the firsts two cases (cases 1 and 2), genetic analysis of tumour samples showed nor LOH neither CNV for CDKN1B, findings that agree with those in the literature." (PMID 36334246, 2023). "Predictors composed of mixed clinical and omic features were also considered, finding good and performance, confirmed in independent cohorts, for a fingerprint composed of three well known clinical parameters (PSA, Gleason primary score, and tumor stage) and expression levels for NF2 and CDKN1B." (PMID 37188913, 2023). "Given the tumor-suppressive roles of CDKN1B and CDKN1C, miR-222-mediated down-regulation of CDKN1B and CDKN1C may contribute to Ni-induced tumorigenesis or tumor progression." (PMID 36497250, 2022). "CDKN1B, FOS, FOXO1, HDAC1, and RB1 were mainly expressed in the nuclear of tumor cells." (PMID 33748162, 2021). "Genetic deletion of Cdkn1a or Cdkn1b does not result in major developmental or proliferation defects but results in spontaneous tumor formation in some tissues of adult mice." (PMID 33078209, 2021). "The availability of organoids and spheroids may finally allow the study of downstream targets of somatostatin and IGF2 in I-NETs as well as the importance of candidate tumor genes like MIR1-2, RASSF1A, APC, or CDKN1B." (PMID 34680217, 2021). "The deubiquitylase USP37 regulates cell proliferation by acting on the stability of the cyclin-dependent kinase inhibitor 1B (CDKN1B/p27Kip1) and may act as a tumor suppressor in MB." (PMID 34681949, 2021). "Further, CDKN1B is described as haplo-insufficient tumor suppressor gene, where animals lacking one copy of CDKN1B already displayed tumor-prone phenotypes." (PMID 34805186, 2021). "Impaired NOTCH1 activity may result in the activation of specific oncogenes (c-MYC, NFkB, or mTOR) or inhibition of tumor suppressor expression (FBXW7, PTEN, CDKN1B)." (PMID 32766158, 2020). "CDKN1B is downregulated in different tumors according to a number of studies, and based on this, this protein has been identified as a noncanonical tumor suppressor gene." (PMID 32590883, 2020). "In addition, CDKN1B and ING5 downregulation in HNC was closely related to increased tumor size, lymph node metastasis, advanced tumor stage, and chemoresistance, which eventually contributed to the poor prognosis in HNC patients." (PMID 30642385, 2019). "The CDKN1B gene was the first gene described as haplo-insufficient for tumor suppression, meaning that it did not follow the Knudson's “two-hit” theory." (PMID 30065701, 2018). "Studies in patients with MEN1-like tumours, but without MEN1 mutations, revealed some to have CDKN1B mutations." (PMID 26320859, 2016). "However, transfection of miR-221 inhibitor suppressed the proliferative capacity of PDAC cells with concomitant upregulation of CDKN1B, as well as of PTEN and PUMA, which are other tumor suppressors among the predicted targets of miR-221." (PMID 25250326, 2014). "For instance, miR-224 increases tumor cell progression by inhibiting the expression of apoptosis inhibitor-5, and miR-221 promotes cell proliferation by controlling the cell cycle inhibitors (CDKI) CDKN1C/p57 and CDKN1B/p27." (PMID 26835673, 2013). "Consequently, we show that IRF4 controls the expression of tumour suppressor genes known to be silenced by these epigenetic modifications, for instance cyclin-dependent kinase inhibitors CDKN1A and CDKN1B, the PI3-AKT pathway regulator PTEN, and primary cilium components." (PMID 38880659, 2024). "Interestingly, although CDKN1B (gene name for p27) remained elevated by the bone-disseminated tumor cells expressing PTHrP lacking the NLS and C-terminal domain, the cells readily colonized the bone marrow." (PMID 38409028, 2024).
tumor (continued). "Low CDKN1B expression was significantly correlated with low lymphocyte-infiltrating signature scores (p < 0.001), decreased B cells (p < 0.001), decreased CD8+ T cells (p = 0.04), high tumor cell proliferation (p = 0.04), low leukocyte count (p < 0.001), and elevated M2 macrophages (p < 0.001)." (PMID 38248731, 2023). "Protein p27, cyclin dependent kinase inhibitor 1B, was previously found to bind and inhibit cyclin-CDK to arrest the cell cycle, and recently p27 was also reported to function as an oncogene to involve in tumor migration, invasion and regulation of gene expression in tumor." (PMID 37089937, 2023). "However, while CDKN1B mutant mice make a variety of tumors, I-NETs are not among the tumor types that have been reported in these animals." (PMID 34680217, 2021). "However, the treatment failed to reactivate other epigenetically silenced tumour suppressors like CDKN1B (p27) or CDKN2A (p16) (data not shown)." (PMID 30214687, 2018). "Animals lacking only one copy of Cdkn1b already displayed a tumor-prone phenotype, with increased tumor frequency and decreased latency when challenged with different carcinogens and spontaneously developed pituitary tumors with a mild penetrance, late in life." (PMID 30065701, 2018). "In addition, S-phase kinase-associated protein 2 (Skp2) specifically degrades cyclin-dependent kinase inhibitor 1B (CDKN1B), and mindbomb homolog 1 (MIB1) enhances the ubiquitin-mediated degradation of suppression of tumorigenicity 7 (ST7); both Skp2 and MIB1 promote tumor proliferation." (PMID 38174069, 2023). "Finally, analysis of polysomal RNAs from livers of CTL and TIA1 knockdown LPTENKO mice indicated that consistent with a lack of effect of TIA1 downregulation on tumor growth and progression, markers for proliferation (Mki67, Pcna, Cdkn1a, Cdkn1b, Cdc25a) and inflammation (Il1b, Tgfb) were unchanged." (PMID 35406476, 2022). "The target mRNAs CDKN1B, TGFR1, and IGF1R showed no significant change between tumor and non-tumor tissue." (PMID 40630212, 2025). "To explore the role of QCCs in MEL101, we quantified tumor cells that were negative for KI67 and positive for either or both of p21 (CDKN1A) and p27 (CDKN1B)." (PMID 41473281, 2025). "CDKN3 is a relatively unique member of the CDKN family because overexpression of CDKN3 has been proven to be oncogenic in multiple cancer types 41, unlike the tumor suppressive CDKNs, such as CDKN1A and CDKN1B." (PMID 38356706, 2024). "Most of these genes (STAT5B, CDK6, CDK2, CDKN1B, E2F8, and E2F1) showed high mRNA expression in tumor tissues compared to adjacent non-tumor tissues." (PMID 32807134, 2020). "Although CDKN1B appears to inhibit the development of tumors, genetic investigations of MEN4-related tumors are limited in numbers and not consistently supporting that CDKN1B is a tumor suppressor gene." (PMID 30990521, 2019).